FOXP3 (forkhead box P3)
Diseases named in the same sentence as FOXP3 in open-access papers (continued):
Sharing a sentence is not in itself a finding about the gene and the disease.
tumor (continued). "There are also contrasting prognostic effects of the Foxp3/CD4 ratio in CGC and NCGC, which suggests that location may be an important factor for tumor progression." (PMID 34926251, 2021). "It is reported FoxP3+Treg cells secrete TGF-β, which means that the suppression of anti-tumor immunity of FoxP3+Treg cells may be cytokine-dependent." (PMID 34654443, 2021). "Herein, approximately 30% of late-stage UC tumor specimens exhibited high CD8, PD-1, and FOXP3 expression levels, which could be improved by anti-PD-1 or anti-PDL1 therapy." (PMID 35052695, 2021). "FOXP3 alone fails to predict patient survival and its prognostic value is tumor type- and stage-dependent across different cancers." (PMID 34599187, 2021). "Tumor slides were immunohistochemically stained for CD3, CD8, CD4, CD20, CD38 and FoxP3." (PMID 33006650, 2021). "Combination therapy promoted a significant and sustained reduction of CD4+FoxP3+ Tregs in the EMT6 TME, without significantly affecting FoxP3− CD4+ tumor-infiltrating lymphocytes (TILs)." (PMID 34446712, 2021). "Conventional T cells included conventional CD4+ T cells (cluster 4 in Paratumor and cluster 3, 8, 11 in Tumor; CD4+), regulatory T cells (cluster 8 in Paratumor, and cluster 5 in Tumor; FOXP3+), CD8+ T cells (cluster 2, 5, 10 in Paratumor, and cluster 0, 1, 2 in Tumor; CD8A+)." (PMID 33429363, 2021). "A study of DHA in melanoma showed that DHA induced the proliferation of IFN-γ+CD8+ T cells in tumor microenvironment and mouse spleens, while the number of CD4+CD25+Foxp3+ T cells and IL-10+CD4+CD25+ T cells returned to normal, thus enhancing the anti-tumor immunity of mice." (PMID 33613116, 2021). "Moreover, hypoxic conditions as a result of increased tumor growth and oxygen deprivation stabilize the expression of hypoxia‐inducible factor 1‐α (HIF1‐α), which in turn mediates the induction of FoxP3 expression and favors Treg stability." (PMID 33532902, 2021). "The involvements between FOXP3 and tumor immunity have not been clearly illustrated, and current results of tumor FOXP3 are inconsistent and inconclusive." (PMID 34992605, 2021). "Of note, the CD8/CD4 and CD8/CD4 Foxp3 ratios remained unchanged, likely reflecting a non-selective increase in lymphocyte tumor infiltration upon TSP1 knockdown." (PMID 34439212, 2021). "Moreover, within the tumor region, they had a lower density of total CD4+ cells and a lower CD4 + FoxP3+/CD8 + Granzyme B+ cell ratio." (PMID 33947438, 2021). "Within all tumors, the loops formed by the FoxP3+ cells have larger radii than the other cell types, but this is not significant for the best oxygenated tumor." (PMID 34625491, 2021). "PD-1 expressing Foxp3+CD4+ regulatory T cells in the tumor can block the function of effector T cells, and therefore, it was important to define the effects of regulatory T cells on tumor growth and immunity." (PMID 34912335, 2021). "In the present study, we aimed to characterize the population of tumor-infiltrating immune cells (CD3+, CD4+, CD8+, Foxp3+, and CD57+) along the ACS, and to uncover potential differences between adenomatous and invasive lesions in the sporadic setting versus the hereditary (FAP-related) context." (PMID 34575971, 2021). "Among T cells, FoxP3+ Tregs are the most resistant sub-population of T cells and their number is not strikingly different between irradiated and non-irradiated tumours." (PMID 34299373, 2021). "Furthermore, expression of Foxp3 and IL-10 was reduced in CD4+CD25+ gated cells isolated from tumor bearing mice treated with TAK-242 in comparison to vehicle-treated controls." (PMID 34771569, 2021). "This Treg-specific demethylated region is required for the long-term maintenance of FOXP3 expression, which may mediate by the superfluous STAT5 and TET2 in tumor-infiltrating Treg cells." (PMID 34177907, 2021). "While in other studies, a correlation between FoxP3+ Tregs and tumor stage or prognosis in CM has not been found." (PMID 34051744, 2021).
tumor (continued). "We found that the expression of FOXP3 and CCR4, and the percentage of CD4+FOXP3+ and FOXP3+CCR4+ Tregs chemoattracted to the tumor sites were significantly downregulated in the shL1CAM group, but upregulated in the L1CAM overexpression group, as compared with the control." (PMID 33710805, 2021). "This is possibly because the FOXP3+ (lo) non-Treg T cell population leads to an inflammatory TME against the tumor." (PMID 33809974, 2021). "Although TGFβ expression was not changed with CHK1i+LDHU treatment, this cytokine is strongly expressed in these tumours suggesting that intra-tumourally recruited CD4+ T and NKT cells are converted into FoxP3+ regulatory cells by the high levels of TGFβ in the tumour microenvironment." (PMID 34359633, 2021). "Treatment of LLC-OVA tumor-bearing mice with Nb-Fc1B (treatment schedule) resulted in the complete depletion of CCR8+ Tregs in the TME, whereas CD4+Foxp3− T cells remained unaffected." (PMID 33589525, 2021). "Additionally, the percentage of FoxP3+γδTc is inversely correlated with CD8+ TILs, confirming the anti-tumor immunosuppressive role for γδTc and poor clinical outcome." (PMID 33532902, 2021). "Interaction of PD-1 with its ligands leads to an inhibitory effect on the activation of T-lymphocytes, an increase in the number of Foxp3+ T-regulatory cells and inducing of apoptosis of CD8+ cytotoxic T-lymphocytes, which allows the tumor to “escape” the immune response." (PMID 34943606, 2021). "We further analyzed the tumor, spleen, and peripheral blood and found increased numbers of CD3+ T (both CD4+ and CD8+ T cells) in the combination-treatment groups, whereas the numbers of CD4+ FoxP3+ T cells were decreased." (PMID 33859948, 2021). "In subcutaneous transplant tumor mice and colitis-associated cancer (CAC) mice, romidepsin increased the percentage of FOXP3+ regulatory T cells (Tregs), decreased the ratio of Th1/Th2 cells and the percentage of IFN-γ+ CD8+ T cells in the peripheral blood and the tumor microenvironment." (PMID 32632663, 2021). "CD25hi forkhead box P3 (Foxp3)+ regulatory T cells (Tregs) are an essential endogenous population of CD4+ T cells that act as potent immunosuppressive cells to control autoreactive immune responses and limit tumor immunity." (PMID 33708206, 2021). "Dividing the cases by tumor subtype, the FOXP3+ survival improvement was observed in UUS, and as a nonsignificant trend in ESS (p = 0.0269 and p = 0.0954, respectively), but not in LMS." (PMID 34799669, 2021). "A six-plex panel was specifically designed to interrogate the tumour-immune microenvironment and included a tumour-related protein (cytokeratin), a functional marker for proliferation (Ki67) and four immune-related T-cell lineage markers (CD3, CD4, CD8 and Foxp3)." (PMID 33742063, 2021). "Additionally, tumor-derived exosome-mediated release of IL-10 will activate JAK/STAT-3 pathway and stabilizes FoxP3 expression and differentiation of pTregs." (PMID 33532902, 2021). "We analyzed the density, quality, and temporal distribution of tumor-infiltrating immune cells (CD3+, CD4+, CD8+, Foxp3+, and CD57+), as well as molecular and immunophenotypic biomarkers of tumor immunogenicity, along the development of colorectal precursor and invasive lesions." (PMID 34575971, 2021). "Overall, the median of CD8+/FOXP3+ ratios increased significantly post NACT in the stromal (p = < 0.0001) and intra-epithelial compartments (p = 0.0007) as well as the median of intra-epithelial CD3+/FOXP3+ ratios (p = 0.006) favoring anti-tumor immunity." (PMID 32852603, 2021). "Included factors were primary tumor (T) (I, II vs III, IV), N stage (N0 vs N1–3), tumor grade (well to mod vs poor), lymphatic invasion, vascular invasion, neural invasion, SKP2 expression, Beclin-1 expression, tumoral FOXP3 expression, and number of Tregs (<15/HPFs, ≥15/HPFs)." (PMID 34414959, 2021).
tumor (continued). "As our previous studies have shown, RFS was also correlated with PD-L1 on TILs, and CD3, CD4, CD8, and FOXP3 on immune cells but not with PD-1 on TILs and PD-L1 on tumor cells." (PMID 34362829, 2021). "The tumor samples were stained for CD68 (total macrophage marker), CD163, CD206, CD204, CHID1 (M2 markers), inducible nitric oxide synthase (iNOS), IDO1 (M1 marker), FoxP3 (Treg marker), CD3 (mature T-cells marker), CD8, and PD-L1." (PMID 33466316, 2021). "Furthermore, its combination with HSP70 vaccine induced a potent anti-tumor immunity by increasing the expression of Th1 cytokines, IL-2, and IFN-γ and decreasing transcription levels of IL-10, TGF-β, and Foxp3 in the tumor microenvironment." (PMID 34531847, 2021). "Correlation of CD8 counts or FoxP3 counts between the tumor vs. non-tumor region was not statistically significant." (PMID 34257613, 2021). "Tumor-infiltrating lymphocytes (TILs) are highly heterogeneous population which include B lymphocytes, CD8+ cytotoxic T lymphocytes, cytokine-secreting CD4+ T helper lymphocytes, and Forkhead box P3 (FoxP3)+ Tregs." (PMID 33579265, 2021). "Notably, in spite of the elevated number of T cell players found in the tumor microenvironment, the most consistent survival predictors are (i) the number of TILs and (ii) the ratio between CD8+ cytotoxic T cells and CD4+ FOXP3+ Tregs." (PMID 34787568, 2021). "The percentage of intratumoral Foxp3+Helios+ Tregs was markedly higher in tumor tissue than in peripheral blood, but there was no significant alteration in the different stages of cancer." (PMID 34257746, 2021). "Spatial analysis revealed a differential distribution according to immune cells proximity to the tumour, with a decreasing proportion of proliferating CD3+ (P < 0.001), CD8+ (P < 0.001), CD4+ (P < 0.001) and Foxp3+ (P < 0.001) T cells from the intratumoural region (A) to the distal location (C)." (PMID 33742063, 2021). "Meanwhile, administration of low-dose TSA in tumor-bearing mice did not result in significant changes in the frequency of Foxp3+ Treg cells in TILs, spleen and blood in tumor-bearing mice." (PMID 33564072, 2021). "In an in vitro study, blockade of CD200 expression in CLL (by anti-CD200 antibody or siRNAs) decreased the number of CD4+CD25+Foxp3+Treg, enhanced production of the proinflammatory cytokines IFN-γ and TNFα by effector PBMCs, and augmented effective killing of tumor cells by CD8+ CTL." (PMID 33562512, 2021). "High numbers of tumor-infiltrating Foxp3+ Tregs and decreased ratios of tumor-infiltrating CD8+ T cells in the tumor infiltrate are correlated with promoting tumor development and progression in several tumor types." (PMID 35250965, 2021). "Next, in order to assess whether Itgβ8 expression by Tregs confers their abilities to control the anti-tumor immune responses by providing a bioactive source of TGF-β, we first selectively ablated Itgb8 in Tregs, using Foxp3-Cre Itgb8fl/fl mice (Foxp3ΔItgβ8)." (PMID 34711823, 2021). "The exact mechanism between tumor and immune microenvironment remains undetermined, but new biomarkers such as CD8 and FOXP3 may contribute to the stratification of patients and a better understanding of these survival curves." (PMID 34885199, 2021). "We found it particularly important that the ratio of CD8+ TNFR2+ PD-1+ TILs over either of these two subsets of CD4+ TNFR2+ TILs (CD4+ TNFR2+ FOXP3+ and CD4+ TNFR2+ PD-1+) was significantly increased in chemotherapy-treated mice and was strongly connected to reduced tumor volumes." (PMID 34201054, 2021). "In this work, we analyzed the predictive and prognostic capacity of several parameters related to the immune response to the tumor (i.e., NLR, PD-L1, CD8+, and FOXP3+ TILs) using a selected cohort of advanced HNSCC patients included in an organ-preservation protocol and treated with ICT." (PMID 33923066, 2021).
tumor (continued). "We have not demonstrated formally that ectopic FOXP3 expression is exerting a direct tumor-suppressive activity on 4T1 tumor cells." (PMID 33671179, 2021). "Moreover, the number of tumor infiltrating CD4+ and Foxp3+ lymphocytes were independent prognostic factors for survival in BTC." (PMID 34573939, 2021). "Conversely, patients without FoxP3- tumor cells and high Tregs had worse outcomes than all other groups." (PMID 34141625, 2021). "Altogether, tumor growth inhibition after PD-1 blockade was due to the expansion of CD8+ T cells expressing the costimulatory molecule ICOS and a concomitant reduction in the frequency of CD4+Foxp3+ regulatory T cells." (PMID 34912335, 2021). "Furthermore, the fusion protein vaccine inhibited tumor growth and improved the tumor microenvironment in vivo, with more CD3+ cells and fewer FOXP3+ cells in the tumor." (PMID 34358202, 2021). "Pre-treatment biopsies and post-treatment tumor resections were analyzed by mIF (PerkinElmer Vectra) using an antibody panel that characterized tumor cells (cytokeratin-positive), immune cells (CD3, CD8, CD163, FoxP3), and PD-L1 expression." (PMID 33413574, 2021). "In addition, the correlation between FoxP3+ Tregs and IDO+ stromal immune and IDO+ tumor cells was examined." (PMID 34051744, 2021). "We failed to investigate the correlation between FOXP3 expression and PD-1 levels on tumor cells for the limited samples." (PMID 34006632, 2021). "In addition, analysis of two published datasets provided evidence that the expression of CCL5 was positively correlated with Tregs (FOXP3) in HCC tumor tissues and PoV tumor thrombus." (PMID 34215748, 2021). "In the context of the tumor microenvironment, CD4+CD25+FOXP3+ Tregs have been extensively studied." (PMID 33802331, 2021). "Moreover, local tumor immune-related cells (CD3+, CD4+, CD8+, PD-1+, and Foxp3+ T cells) were also evaluated." (PMID 34758773, 2021). "Th17 cells and CD4+ CD25+ Foxp3+ regulatory T cells, and immunoregulatory cytokines such as TGF-β, may play equivocal roles in tumor development, depending on their context within the TME and triggering events leading to initial propagation of carcinogenesis." (PMID 34930302, 2021). "CD133, CD44, CD34, FOXP3, PDL1, LDH, and VEGF for assessing tumor cell inhibition." (PMID 37305162, 2021). "If any genes upregulated or downregulated in tissue Treg, non-tumor diseased Treg and tumor Treg are not collaborated with Foxp3 regulation, they will be placed in non-collaboration gene groups." (PMID 34084175, 2021). "For the expression level of FOXP3 that is proportional to the amount of TI-Tregs in the tumor sample, no prediction power was observed for overall survival as expected." (PMID 33598101, 2021). "Finally, mice transplanted with NR-FMT stool disclosed a rise in RORγT+ T helper 17 tumor-infiltrating cells and higher densities of regulatory CD4+FoxP3+ T cells and CD4+IL-17+ T cells in the spleen, indicating a compromised immune response by the host." (PMID 34360802, 2021). "However, the percentage of Foxp3+ cells in CD4+ T cells was increased in the spleen, blood, and tumor tissue by 15%–50% in mice treated with BLM (P < 0.05)." (PMID 34378880, 2021). "Moreover, although a recent study reported that cancer cells produced TGF-β1 in tumor supernatants and when CD4+ T cells were cultured in tumor supernatants, FOXP3+ Tregs generation was promoted." (PMID 34026621, 2021). "In addition, we found a significant inverse correlation between alpha-SMA and FoxP3 (marker of Tregs) mRNA expression in a microarray analysis involving 78 HCCs, thus suggesting that TGFβ-activated stromal cells may counteract the trafficking of Tregs into the tumor." (PMID 34769191, 2021). "In addition, the infiltrating CD8+ T cells in rechallenged tumor were remarkably increased in the ES-DSM + MW group, while Foxp3+ T cells (Tregs) were greatly reduced, further emphasizing the importance of the immune response in the antitumor process." (PMID 34362890, 2021).
tumor (continued). "Programmed death-ligand 1 (PD-L1) and indoleamine 2,3-dioxygenase 1 (IDO1) expression and signal-regulatory protein alpha (SIRPα), forkhead box P3 (FOXP3), and cluster of differentiation 8 (CD8) infiltration were assessed by immunohistochemical studies of 137 tumor tissues from 96 patients." (PMID 34285260, 2021). "The variables associated with overall survival were the lack of expression of PTEN in tumor cells and the number of cells positive for FOXP3." (PMID 34362334, 2021). "In low-risk patients, we identified significantly higher numbers of CD68 +, PD-L1 + CD68 + and PD-L1 + FOXP3 + cells in the stroma relative to tumour (n = 9) (CD68 +: p = 0.0117, PD-L1 + CD68 +: p = 0.0039, PD-L1 + FOXP3 + CD4 + p = 0.0039, paired samples Wilcoxon signed-rank test)." (PMID 34359755, 2021). "Tumor-infiltrating CD4+ cells consisted of FOXP3+CD127− Treg, FOXP3−CD127+ Tconv but also a major proportion of FOXP3+CD127+ ActTconv, which according to the single-cell transcriptome analysis above resemble cluster 1 and, thus, possess an activated phenotype with immune-suppressive properties." (PMID 33602930, 2021). "The data indicate that a chemotherapy-induced up-regulation of CD8+ TNFR2+ and CD8+ TNFR2+ PD-1+ TILs at the expense of CD4+ TNFR2+ FOXP3+ TILs and CD4+ TNFR2+ PD-1+ TILs was connected to reduced tumor growth, possibly through alteration in anti-tumor immune activities." (PMID 34201054, 2021). "Tumor cells that are known to produce a variety of immunosuppressive factors such as PGE2, ADO, IL-10, and TGF-β, appear to play a major role in the conversion of CD4+CD25neg precursors to CD4+CD25+CD39+FOXP3+ Treg." (PMID 34442398, 2021). "Furthermore, considering the complexity of the tumor immune microenvironment, the prognostic values of other intratumoral-infiltrating T-cell subgroups, such as CD4+, FOXP3+ T-cells, are needed for further exploring." (PMID 34717647, 2021). "Like CD8+ T cells, CD4+FoxP3+ Treg cell infiltration was low in all treatment groups, but both age and stress effects were revealed, as well as relationships with circulating corticosterone and CD4+ T cell and macrophages tumor infiltration." (PMID 34604038, 2021). "Whereas a substantial proportion of Foxp3+ Treg cells within tumours of WT animals were positive for anti‐CCR8 antibody staining, this signal was abolished upon cells infiltrating tumours of Ccr8−/− animals, confirming both the target and specificity of the antibody used." (PMID 33838058, 2021). "Treatment-induced depletion of Foxp3+/CTLA4+ Tregs was only seen in tumor samples, but not in the peripheral blood." (PMID 32681091, 2020). "This may explain the increased proportion of CD4+/Foxp3+ Treg in PLNs, accompanied by a decreased proportion of CD8+ T lymphocytes in PLNs and the tumor infiltrate, from T. canis infected mice." (PMID 32547942, 2020). "Flow cytometry analyses of cells isolated from CT26 tumors on day 13 indicated that 45 ± 3% of the CD4+ TILs were Tregs (FOXP3+), and 54 ± 2% of the tumor-infiltrating Tregs expressed GARP, regardless of the treatment." (PMID 32917858, 2020). "Tumor-infiltrating lymphocytes expressing CD8, CD4 and Forkhead box 3 (Foxp3) were detected by IHC." (PMID 32284765, 2020). "• Both ipilimumab and tremelimumab increase the infiltration of CD4+ and CD8+ cells without significantly changing or depleting FOXP3 cells within the tumor microenvironment." (PMID 32265933, 2020). "Single immune cells were detected with trained algorithms in annotated tumor, invasive margin and normal colon ROI and cell densities of CD11b+CD14+, CD11b+CD15+ and ARG1+ myeloid cells, and CD8+Ki67+/–, CD8+Ki67+/– and FOXP3+ T cells were computed respectively." (PMID 33193316, 2020). "Consistent with the reduction in tumor size, we found increased numbers of hematopoietic and T cell infiltrates However, we did not see differences in Foxp3 or PD-1 expression in the tumors from mice treated with the Lpx control or the G12D1–23–Lpx." (PMID 33298945, 2020).